IL1B (interleukin 1 beta)
Diseases named in the same sentence as IL1B in open-access papers (continued):
Sharing a sentence is not in itself a finding about the gene and the disease.
bladder cancer (continued). "Herein, we demonstrated that EGCG could inhibit this stimulating action of IL-1β on bladder cancer cells." (PMID 36430487, 2022). "Interestingly, it was shown that the proinflammatory cytokines IL1A and IL1B are most probably also related to bladder cancer invasion." (PMID 34070905, 2021). "With the recombinant IL-1β (Invitrogen, Waltham, MS, USA) added into the culture medium of MB49 cells for determining the potential impact on survival of bladder cancer cells, clonogenic survival in irradiated bladder cancer cells was reduced with the added IL-1β protein in a dose-dependent manner." (PMID 31766169, 2019). "In primary localized bladder cancer, particularly after cisplatin exposure, the surrounding tumor microenvironment may promote IL-1β production by inflammatory lymphocytes." (PMID 27698389, 2016). "Treatment with phorbol ester, interleukin-1 beta, or interferon gamma increased the level of G-CSF, granulocyte-macrophage colony-stimulating factor, and macrophage colony-stimulating factor in an in vitro bladder cancer cell line study." (PMID 24885603, 2014). "Notably, cisplatin treatment significantly promoted the expression of these cytokines in GFP-knockdown but not Hotair-knockdown cells, indicating that knockdown of Hotair abolished cisplatin-induced upregulation of IL-6, TNF-α, and IL-1β in mouse bladder cancer cells." (PMID 36471329, 2022). "We found that the high expression level of IL-1β correlates with RFS, CSS, and OS in bladder cancer and is an independent predictor of the outcome in the multivariate analysis." (PMID 38397123, 2024). "From the human data, the urine of bladder cancer patients had significantly upregulated levels of CCL2, IL-6, CXCL10, IL-1b, IFN-g, TGF-b, and IL-8 in comparison to the healthy donors." (PMID 37901214, 2023). "In comparison to healthy donors, CCL2, IL-6, CXCL10, IL-1b, IFN-g, TGF-b, and IL-8 were enriched within the urine of bladder cancer patients." (PMID 37901214, 2023). "An analysis of the overall survival of patients with bladder cancer was conducted using the GEPIA2 database to verify the accuracy of uPAR and IL1B expressions." (PMID 36430487, 2022). "Taken together, these results indicate that forced expression of HOTAIR or ProT in human bladder cancer cells enhances the expression of IL-6, TNF-α, and IL-1β." (PMID 36471329, 2022). "For verification, the cytokine effects on other bladder cancer cell lines, such as TCC-SUP and 5637, were examined, and IL-1β increased the AKR1C1 levels in both cell lines." (PMID 27698389, 2016). "Moreover, we found that silencing LINC00482 inhibited inflammation and angiogenesis in bladder cancer through the down-regulation of MMP-15 by targeting FOXA1, along with decreased levels of TNF-α, IL-1β, and IL-6 as well as the expression of VEGF and NF-κB." (PMID 33323547, 2020). "The IL-1β protein had no significant impact on clonogenic survival of non-irradiated bladder cancer cells." (PMID 31766169, 2019). "IL1b, IL6, GMCSF, MCSF, GCSF, and TNFα are expressed in a human bladder carcinoma cell line." (PMID 22013484, 2011).
cardiomyopathy (26 papers, 2010 to 2025). A disease of the heart muscle or myocardium proper. "Positive findings, in turn, included association between increased risk of cardiomyopathy and the CT haplotype for the IL1B −31 T>C and +3954 C>T (rs1143634, synonymous coding sequence variant) polymorphisms in Colombia." (PMID 33193300, 2020). "We also describe novel associations between specific IL18, IL17A, and IL1B variant profiles and the risk of cardiomyopathy as well as between a specific IL6 polymorphic genotype and the risk of positive T. cruzi parasitemia." (PMID 33193300, 2020). "Moreover, association between cardiomyopathy and the IL1B +5810 G>A (rs1143633, intronic SNV) G allele and GG genotype was also identified, despite no established effect of this allele or genotype on IL1β production." (PMID 33193300, 2020). "Another study demonstrates that inhibition of the NLRP3/IL-1β pathway mitigates cardiac atrophy and cardiomyopathy in septic mice." (PMID 39887250, 2025). "Herein we investigated potential associations between IL1B, IL6, IL17A, or IL18 polymorphism profiles and cardiomyopathy or T. cruzi parasitemia, as well as the impact of HIV infection on cardiopathy." (PMID 33193300, 2020). "Dox-induced cardiomyopathy is also associated with increased levels of the MMP2- and 9, and pro-inflmammatory cytokines TNF-α, IL-1β, and IL-6 as similar to the results observed in kidney." (PMID 25742619, 2015). "Facing the biological and clinical scenarios just described, in the current study we investigated potential associations between SNVs linked to IL1B, IL6, IL17A, or IL18 and the risks of positive T. cruzi parasitemia or development/progression of cardiomyopathy." (PMID 33193300, 2020). "Likewise, the different pathways of IL-1β activation demonstrated here may be studied as a parameter of pharmacological intervention in order to prevent the evolution of cardiomyopathy, fibrosis and inflammation in the pathogenesis of Chagas disease." (PMID 31057540, 2019). "To demonstrate the anti-inflammatory effects of AKBA, we assessed the production levels of proinflammatory cytokines, including TNF-α, IL-6, IL-1β, and PGE2, which contributed to LPS-induced cardiomyopathy." (PMID 35399644, 2022). "Lnc‐MEG3 expression was positively correlated with cardiomyopathy, APACHE II score, SOFA score, Scr, TNF‐α, IL‐1β, IL‐6, and IL‐17, 28‐day deaths, while negatively correlated with albumin." (PMID 34956235, 2021). "Development of cardiomyopathy has been related to extracellular matrix (ECM) remodeling, which are controlled by matrix metalloproteinases (MMPs) and cytokines, especially interleukin (IL)-1β." (PMID 31057540, 2019). "Thus, an increased level of IL1B expression has been observed in CCC patients, which has led to propose the different activation pathways of this cytokine as a therapeutic target to prevent the evolution of cardiomyopathy, fibrosis and inflammation in Chagas disease." (PMID 37440604, 2023).
Erythema (26 papers, 2013 to 2026). Redness of the skin, caused by hyperemia of the capillaries in the lower layers of the skin. "Clinically, elevated IL-1β levels were associated with the presence of erythema and urticarial plaques reflecting the inflammatory phase preceding blister formation." (PMID 31507596, 2019). "Clinically, IL-1β associated inflammasome was related to the presence of erythema and urticarial plaques, which are representative clinical signs of the early inflammatory phase preceding blister formation." (PMID 31507596, 2019). "The resolution of erythema and scales in the artemether‐treated group might be associated with its inhibition of molecules related to the innate immune response in SD lesions, such as IL‐1β, IL‐8, and the NF‐κB pathway." (PMID 40980936, 2025). "Compared to their wild-type counterparts, Keap1-knockdown mice have lower expression of the pro-inflammatory cytokines IL-6 and IL-1β and display reduced cutaneous erythema following acute exposure to solar-simulated UVR." (PMID 35753587, 2022). "The erythema, barrier function, and epidermal thickness of the AD-like wounds were improved by CoQ0 through the reduction of IL-1β, IL-4, IL-6, IL-10, interferon (IFN)-γ, and by neutrophil infiltration in the lesional skin." (PMID 31849685, 2019). "Our results showed that UV exposure induced erythema, edema, and epidermal hyperplasia of the mice skin, while upregulating the levels of IL-1β, IL-6, TNF-α, and IL-10 in mice skin significantly." (PMID 26903706, 2016). "We found that topically applied IPyr ameliorated dorsal skin erythema in the UVB-irradiated mice diminished transepithelial water loss and reduced the mRNA expression of IL-1β, IL-6, Cox-2, and Bax." (PMID 24810606, 2014). "Fatigue symptoms, erythema, and cytokine levels (IL-1β, IL-2, IL6, IL-8, TNF-α, and MCP-1) were registered at baseline, during treatment, and after radiotherapy completion." (PMID 24800238, 2014). "Gal‐3 regulates ultraviolet‐induced skin inflammation by modulating the production of inflammatory cytokines, reactive oxygen species, and phosphorylation of p38 in human keratinocytes, while its knockout attenuates erythema, tissue inflammation, and expression of active IL‐1β and COX2 in mice." (PMID 39230472, 2024). "Indeed, IL-1β biological activity displayed a positive and significant correlation between the IL-1β levels in BF or the inflammatory ratio IL-1β/IL-1RA and the erythema/urticaria BPDAI subscore, suggesting its involvement in the early inflammatory phase." (PMID 31507596, 2019). "IL-1β concentration in the BF was correlated with the skin erythema/urticaria activity (n = 25; r = 0.55; p = 0.0048), but neither with the total BPDAI score (n = 25; r = 0.29; p = 0.15), nor with the skin BPDAI subscore associated with blisters and erosions (n = 25; r = 0.11; p = 0.62)." (PMID 31507596, 2019). "Additionally, genetic predispositions influencing inflammation, such as variations in interleukin genes (e.g., IL‐6, IL‐1β), may affect the degree of erythema and scarring, leading to differing outcomes among patients receiving the same treatment." (PMID 40414816, 2025). "ABT, APS, and ABPS all reduced the erythema of ear acne, decreased microcirculation in localized ear acne, and decreased serum levels of TNF-α and IL-1β in rats." (PMID 37159798, 2023). "This study demonstrated that H(H2O)m prevented UV-induced erythema and DNA damage in human skin and also inhibited UV-induced MMP-1, COX-2, IL-6 and IL-1β expressions significantly." (PMID 23637886, 2013). "The results showed that PZH could alleviate the erythema and swelling of hind paws of CIA mice, improve the pathological conditions of joint and decrease the production of IL-1β, IL-6 and IL-17 in serum and joints." (PMID 32256686, 2020).
Erythema (continued). "Crucially, these injections did not induce noticeable erythema, inflammatory cell infiltration, or upregulation of pro-inflammatory cytokines such as IL-6 and IL-1β, indicating that inflammation is not the primary factor responsible for PEG2000 segments detachment from NVs." (PMID 38296939, 2024). "Also, similar to UV-induced erythema, we found that UV-induced expression of MMP-1, COX-2, IL-6 and IL-1β mRNA were not significantly changed after 30 min or 1 hr treatments of H(H2O)m (data not shown)." (PMID 23637886, 2013).
Hypercholesterolemia (26 papers, 2012 to 2025). An increased concentration of cholesterol in the blood. "As observed in the HCD group, hypercholesterolemia causes lung inflammation through elevated IL-1β and IL-6 levels, which are physiologically compensated by increased IL-10 levels." (PMID 37082028, 2022). "IL-1β precursor is activated into a mature cytokine by triggering the caspase/NLRP3-inflammasome axis secondary to intracellular or extracellular danger-associated signals such as hypercholesterolemia; a detected feature of hypothyroidism." (PMID 40672362, 2025). "In this study, hypercholesterolemia resulted in an increase of IL-1β, and IL-17, with little effect on IL-10." (PMID 35928361, 2022). "The combined simvastatin and ezetimibe therapy reportedly results in a significant reduction in secretion of the pro-inflammatory cytokine IL-1β from monocytes in hypercholesterolemia patients." (PMID 37082028, 2022). "Together, these results suggest that NLRP3 inflammasome-dependent IL-1β production during hypercholesterolemia promotes VSMC phenotype transition to synthetic status via EV machinery, which is controlled by lysosomal AC activity." (PMID 33409276, 2020). "Furthermore, αCD3/αCD28-stimulated PBMCs from men with hypercholesterolaemia produced more of IL-1β, and IL-6 compared with cells from normolipidaemic men." (PMID 37901041, 2023). "Since pravastatin did not ameliorate and actually worsened hypercholesterolemia-induced oxidative stress, this may be causally related to the increased Il-1β in both BMDM and PM." (PMID 35372506, 2022). "In adults with hypercholesterolemia, a purified anthocyanin mixture led to significant reductions in serum CRP, sVCAM-1, and plasma IL-1β compared to a placebo." (PMID 41156509, 2025). "To examine the anti-neuroinflammatory effects of probucol plus cilostazol on focal cerebral ischemia with hypercholesterolemia, we assessed the mRNA levels of MCP-1, VCAM, iNOS, COX-2, TNF-α and IL-1β in the ischemic brain." (PMID 25017431, 2014). "Cardio treatment significantly inhibited hypercholesterolemia, reduced levels of cardiac damage markers including LDH and CK, improved cardiac function, and reduced HFHC diet‐induced increased levels of inflammatory cytokines including TNF‐α and IL‐1β." (PMID 40951583, 2025). "Although a hypothesis linking IL-1β, LDL-R, and the Wnt/β-catenin signaling pathways to vascular calcification in the setting of hypercholesterolemia has been proposed 133, the detailed mechanism is unknown and further investigation is still needed." (PMID 34803503, 2021). "Therefore, induction of IL-1β, IL-6, and TNF-α by LDL(-) in macrophages has a link between LDL(-) and inflammation in hypercholesterolemia." (PMID 31534437, 2019). "Chronic inflammation has been reported to increase under hypercholesterolemic conditions and is the mechanism through which hypercholesterolemia induces tissue damage, resulting in the over-production of pro-inflammatory cytokines such as TNF-α, IL-1β, and IL-6 in the HFD-fed mice." (PMID 31920470, 2019). "Knockout of Il1b did not affect lesion size in the PCSK9-AAV8 model of hypercholesterolemia." (PMID 37701434, 2023).
leukocytosis (26 papers, 2013 to 2026). "Moreover, scorpion venoms could enhance the release of different inflammatory mediators which cause leukocytosis and raise the cytokines levels such as IL1b, IL6, IL8, IL10, TNFa and NO." (PMID 29367926, 2017). "In cases of fever, rash, pharyngitis, and serositis, leukocytosis IL-1β inhibitors (anakinra, canakinumab, rilonacept) are the treatment of choice." (PMID 39335580, 2024). "NF-κB regulates the expression of the cytokines, including interleukin-1 beta (IL-1β) and TNF-α, which are essential mediators of chronic inflammation and are implicated in leukocytosis, hyperplasia, and tissue break down." (PMID 35163984, 2022). "GM-CSF can be responsible, at least in part, for the leukocytosis observed with SCD, and proinflammatory cytokines like IL-1β, which are increased in SCD, can be associated with elevated levels of GM-CSF." (PMID 32411797, 2020). "Slightly elevated levels of IL-1β can induce the release of the adrenocorticotropic hormone, which produces leukocytosis and thrombocytosis." (PMID 32370250, 2020). "The LPS + PM group showed persistent inflammation characterized by BALF leukocytosis, increased IL-1β and IL-6 levels in the lung parenchyma, decreased alveolar air space volume, septal thickening and decreased septa surface density." (PMID 32943719, 2020). "On the other hand, IL-1β mobilizes HSPCs after in vivo administration and induces leukocytosis in mice." (PMID 31089880, 2019). "IL-1β induces fever and leukocytosis in mice, and IL-1β has been demonstrated in the past to be a mobilizing cytokine." (PMID 31089880, 2019). "Under inflammatory conditions, IL-1β stimulates leukocytosis and thrombocytosis by inducing various cytokines (i.e. Granulocyte-Colony Stimulating Factor, IL-6) that are overexpressed in MF; also, IL-1β regulates the survival/proliferation of AL cells." (PMID 27304059, 2016). "IL-1β is among the earliest cytokines activated after UV exposure; it induces vasodilation, fever, and leukocytosis, stimulates IL-6 production, and activates matrix metalloproteinase (MMPs) expression, contributing to photoaging and extracellular matrix degradation." (PMID 41596382, 2026). "In PV patients, high levels of IL-12 are associated with hematocrit; high IL-1β and HGF levels are associated with leukocytosis; low IL-6 and FGF (fibroblast growth factor) levels are associated with hemoglobin concentration; and low GM-CSF levels are associated with thrombocytosis." (PMID 34084749, 2021). "Even though inflammation starts as a local reaction, it associates a systemic acute phase response that involves pro-inflammatory mediators (IL-6; IL-1β; TNF-α), bone marrow response causing leukocytosis, liver response with acute phase proteins (APPs) synthesis." (PMID 31664997, 2019). "The microinjection of IL-1β into the brain induced a rapid leukocytosis." (PMID 25323767, 2014). "In comparison to normal rats, it was found that the CFA-induced arthritic rats exhibited significant leukocytosis and increase in paw volume, LPO level, RF, and IL-1β serum levels." (PMID 33488761, 2021). "However, as IL-1β has cell-type-specific effects, thus inducing neutrophilia, leukocytosis, and thrombocytosis in vivo, it is conceivable that the lack of IL-1RA may enhance IL-1 signaling, which stimulated the proliferation of specific osteoclast precursor subsets." (PMID 32471111, 2020). "LPS-induced rats showed significant leukocytosis, and elevated serum levels of CRP, TNF-α, IL-1β, IL-6, IL-8, MCP-1, malondialdehyde (MDA) and 8-hydroxy-2′-deoxyguanosine (8-OHdG), accompanied with diminished antioxidants." (PMID 30858869, 2019). "In conclusion, we showed that mammary ASR, which manifested itself by an intense milk leukocytosis, was characterized by the production of IL-17A and IFN-γ but the absence of detectable TNF-α, with a low and inconsistent presence of IL-1β and IL-6." (PMID 23696826, 2013).
leukocytosis (continued). "In addition to amelioration of leukocytosis, SBH reduced the circulating levels of inflammatory mediators, including CRP, MCP-1, TNF-α, IL-1β and IL-6 in LPS-induced rats." (PMID 30858869, 2019). "Although signatures and cell composition from sIU and sIA patients were comparable to those of healthy controls, sAU patients displayed a proinflammatory signature enriched for IL-1β–inducible transcripts (IL1B and CASP1) and demonstrated leukocytosis, neutrophilia, and monocytosis." (PMID 28935693, 2017). "However, in this study it was noted that the levels of IL-1β secreted into the intestinal lumen did not correlate with systemic inflammatory markers (leukocytosis and increased platelet count) due to its short half-life and accelerated degradation by proteolytic enzymes." (PMID 37762896, 2023). "It was found that in patients with positive viral DNA results and a low leukocyte count, the levels of IL-1β, IL-6, ICL, IFN-α, IFN-γ, and CD8 were significantly lower compared with children with negative viral DNA tests and persistent leukocytosis." (PMID 34795992, 2021). "It was found that the levels of IL-1β, IL-6, and ICL were significantly higher in patients with high leukocyte counts and signs of inflammation compared with patients who had no leukocytosis." (PMID 34795992, 2021).